E2F1 (E2F transcription factor 1)
Diseases named in the same sentence as E2F1 in open-access papers (continued):
Sharing a sentence is not in itself a finding about the gene and the disease.
tumor (continued). "Furthermore, there was a reduction in tumor burden showing a decrease from an average of 2.5 tumors per mouse in wildtype E2Fs to 1.5 tumors per mouse in the E2F1 null background." (PMID 26682278, 2015). "These literatures indicated a synergic effect of E2F1 and miR-34c in inhibiting tumour progression." (PMID 26704889, 2015). "Enhanced invasion of advanced GC might be related to the decreased expression of e2f-1, which might transcriptionally regulate down several tumor-suppressing genes and apoptosis-related genes." (PMID 24393368, 2014). "E2F1 mediated apoptosis can act as an important fail-safe mechanism for the elimination of hyperproliferative cells and for the suppression of cellular transformation and tumor formation following disruption of Rb function." (PMID 24809452, 2014). "One critical aspect of our study was to examine whether knockdown of E2F1 in DU145 cell-derived tumor tissues is able to increase expression of ICAM-1 and ICAM-1-mediated leucocytes infiltration in vivo." (PMID 24742333, 2014). "We found that inactivation of either E2f1 or E2f3 can suppress tumor development in the retina." (PMID 25338120, 2014). "Although E2F1 may affect tumor growth through regulating cell cycle or apoptosis, it is interesting to explore whether there is another mechanism of the involvement of E2F1 in tumor growth." (PMID 24742333, 2014). "As such, e2f-1 might potentially inhibit tumor cells and shed new light on the choice of gene therapy for patients with late-stage of tumors after revealing in detail on the more clear mechanism of this regulation." (PMID 24393368, 2014). "The tumor sizes following inoculation of DU145/sh-E2F1 cells were smaller than control cells." (PMID 24742333, 2014). "Because ZNF282 functions as a transcription co-activator of E2F1, which is a critical player in tumor progression, we investigated whether the prognostic effect of ZNF282 in ESCC was influenced by E2F1." (PMID 25373738, 2014). "Our study identifies E2F1 as an important intermediary in this process, with E2F-regulated cell cycle factors accounting for a large proportion of differentially expressed genes in these castrate-resistant tumours." (PMID 24737870, 2014). "In contrast, targeting E2F1 gene suggests a tumour suppressor role." (PMID 24416592, 2013). "Second, eugenol is a potent inhibitor of cell proliferation, may be through inhibition of E2F1 and great increase in the level of the cyclin-dependent kinase inhibitor p21WAF1in vitro and in tumor xenografts." (PMID 24330704, 2013). "The results described here support the pivotal role of cell cycle related proteins, that like E2F1, may act as tumor suppressors or as proto-oncogenes during cancer development, depending on the behavior of their positive and negative regulators." (PMID 23940755, 2013). "Early studies have shown that E2F1 expression can be involved in tumor progression." (PMID 24023875, 2013). "Indeed, such Shh-mediated metabolic reprogramming fuels tumor progression, in an E2F1- and FASN-dependent manner." (PMID 22407012, 2012). "As expected, LCLs knockdown for E2F1 exhibited a reduced growth rate, whereas, in response to DNA damage E2F1 knockdown LCLs were more resistant to apoptosis, indicating that E2F1 acts as both an oncogene and a tumor suppressor in response to different stimuli." (PMID 22438805, 2012).
tumor (continued). "E2F1 protein expression is significantly higher in NSCLC specimens than non-tumor lung tissue." (PMID 23210897, 2012). "It seems that E2F1 plays a dual role in terms of promoting tumor growth and inducing apoptosis." (PMID 23210897, 2012). "Paradoxically, E2F1 can promote apoptosis and function as tumor suppressor." (PMID 23210897, 2012). "Interestingly, whileKi-67 and TOP2A typically stained only a small fraction of tumor nuclei, E2F1 oftenstained the majority of tumor cells." (PMID 21629784, 2011). "ONYX-411 and ONYX-411 armed with K-ras(v12)-specific siRNA, both viruses with tumor selectivity coming from the transcriptional control of the viral genes E1A and E4 by the E2F1 promoter, showed reduced xenograft growth that was more efficient with the armed virus." (PMID 24212620, 2011). "However, when the patient's tumor expressed either high or average E2F1 transcript levels, we also used KIAA0191 expression levels to classify these patients among the various risk groups." (PMID 21453498, 2011). "On the other hand, an unusually high δ-catenin as well as E2F1 expression could indicate the aggressiveness of tumor progression as they could signal that the tumors have already passed the very early stage of the oncogenic buildup." (PMID 21106062, 2010). "Whether the balance of E2F1 activity in a specific tissue leads to apoptosis and tumor suppression vs. proliferation and oncogenesis is likely dependent upon the context of pro- vs. anti-apoptotic signals received by cells at a given time." (PMID 17878947, 2007). "Remarkably, E2F-1 null mice develop unusual spectrum of tumors, indicating that E2F-1 could behave like a tumor suppressor gene." (PMID 17407586, 2007). "We performed a second multivariate Cox model including additionally the 70-gene signature in the NKI data set, reconfirming that E2F1 and the 70-gene signature were significant and additive predictive survival factors together with the nodal status, tumor size and chemotherapy." (PMID 17535433, 2007). "Although knock-out studies in mice suggest that E2F-1 functions as a tumor suppressor, until now no mutation has been reported in human tumors." (PMID 17407586, 2007). "Consistent with others studies, E2F1 levels were upregulated in all tumour types." (PMID 17117177, 2006). "For this we determined first the mRNA expression levels of E2F1 in the same tumours." (PMID 17117177, 2006). "Since we observed that E2F1 overexpression in A375 P0 cells phenocopied ferroptosis-resistance of A375 P3 cells, we then asked whether simvastatin could reverse the ferroptosis resistant properties of E2F1 overexpressed tumor cells." (PMID 41339438, 2025). "A dual-regulated Ad9xHRE1A virus, in which the essential viral E4 gene is driven by the E2F-1 promoter and the E1A gene is controlled by an artificial promoter containing nine tandem hypoxia-responsive elements (HREs) for HIF binding, achieved specific anti-tumor effects in VHL-deficient ccRCC." (PMID 41445946, 2025). "There was a significant reduction in the expression of the proliferation marker Ki67 in the drug-treated mice, and decreased expression of several cell cycle markers including CCND1, and E2F1, which could account for the reduction in tumor weight in response to Bay." (PMID 38994944, 2024). "Moreover, highly expressed E2F1 was observed in a variety of tumor tissues." (PMID 37277745, 2023).
tumor (continued). "Through EIF4A3-mediated E2F transcription factor 1 (E2F1) upregulation, the lncRNA cancer susceptibility candidate 11 (CASC11) inhibited NF-κB and PI3K/AKT/mTOR pathway activation to mediate PD-L1 expression and encourage tumor progression in a mouse model of HCC with lung metastasis." (PMID 35907881, 2022). "E2F1 could mediate the cell cycle and apoptosis of tumor cells." (PMID 35371316, 2022). "In addition, suppression of HDAC3 also resulted in the upregulation of MEG3, a lncRNA tumor suppressor specifically silenced in NFPAs, as well as components in the Rb signaling pathway such as P16 and E2F1, both of which have been suggested to be involved in the pathogenesis of NFPAs." (PMID 35646715, 2022). "However, recent evidence points to a tumor-promoting role of E2F1 in CRC." (PMID 35069909, 2022). "It is suggested that the up-regulation of E2F1 can promote the proliferation, migration, and invasion of these cancer cells, and it is also significantly related to the clinical stage of different cancer types, the depth of tumor invasion, as well as the metastasis and lesion size of lymph nodes." (PMID 36292703, 2022). "However, E2F1 appears to serve both as a tumour repressor and an oncogene in HCC." (PMID 35844791, 2022). "However, certain cell line-based studies showed that ectopic expression of E2F1 could sensitize tumor cells to chemotherapy (etoposide) or radiotherapy in LNCaP or PC3 cells." (PMID 36034466, 2022). "However, whether the promotion and inhibition of E2F1-mediated CSCs regulatory activities are tumor-type specific or miRNAs regulation, which requires further evidences to predict outcome." (PMID 34476219, 2021). "Since ALKBH4 knockdown downregulated the expression of PLK1 and PLK4, ALKBH4 may function as a tumour promoter by accelerating cancer cell proliferation via upregulation of E2F1 signalling in early stage, and by promoting metastasis via upregulation of PLK signalling in late-stage NSCLC." (PMID 33883577, 2021). "In tumor cells, HNF4α downregulation leads to lnc‐APUE upregulation, which may work as a miR‐20b sponge to prevent the miR‐20b‐mediated repression on E2F1 expression, resulting in increase of E2F1 level and in turn acceleration of G1/S transition and tumor growth." (PMID 33854885, 2021). "Hence, E2F1-mediated tumor-related events may be unstable and variable, and they may alter tumor development in response to certain factors." (PMID 34499617, 2021). "In addition, E2F1 in MB regulates lipogenic enzymes, controlling cell proliferation and tumor aggressiveness, and its overexpression is also a documented feature of self‐renewing neural stem cells, where it declines markedly when these cells undergo differentiation." (PMID 32920979, 2021). "Furthermore, E2F1 down-regulation suppressed tumor growth and invasion in bladder cancer." (PMID 34617871, 2021). "Moreover, E2F1 loss also caused loss of VEGFA expression and tumor angiogenesis defects." (PMID 34476219, 2021). "MYC is another well-known oncogene, which could be activated by E2F1 in tumor." (PMID 33791304, 2021). "Previous study found that PVT1 could regulate E2F1 expression levels in tumor development." (PMID 33750300, 2021). "Therefore, MT-MMPs, TGM2 and E2F1 might be conjoined by pathological processes in the liver to trigger inappropriate cell proliferation and tumour development." (PMID 33541355, 2021). "We show that E2F1 transactivates the aerobic glycolysis regulator SLC16A1/MCT1 in parallel with its antisense lncRNA-SLC16A1-AS1 via a shared E2F1-responsive promoter, an event that is particularly associated with tumor progression to muscle-invasive stages and poor patient outcomes." (PMID 32863950, 2020).
tumor (continued). "Furthermore, E2F1/2/7/8 were mainly localized in the nuclei of tumor cells." (PMID 33061852, 2020). "Interestingly, studies in in vivo experimental models highlighted the concept that E2F1 may also display tumor suppressor functions, inducing apoptosis." (PMID 32813746, 2020). "Furthermore, miRNA-106b and miRNA-93 may be upregulated in GC and could be downstream targets of the oncogenic transcription factor E2F1, reducing the effectiveness of the tumor-suppressive function of transforming growth factor-β." (PMID 32206186, 2020). "Since the RB/E2F1 pathway is among the most frequently mutated in many tumour types, we investigated whether the absence of PARP activity could counteract the consequences of E2F1 hyperactivation." (PMID 33050515, 2020). "Thus, it is possible that MELK represents a surrogate marker of E2F1 activation in this tumor type and might be helpful to select people to be treated with CDK4/6 inhibitors." (PMID 31861475, 2019). "The reduced expression of these genes involved in invasion phenotypes may provide additional mechanistic information to explain our previous finding that E2F1−/− tumors had possible invasion/intravasation problems indicated by a reduction in circulating tumor cells." (PMID 31341204, 2019). "In this regards, the existence of a favorable ‘high E2F1/APLF/DCLRE1C’ signature could possibly underscore the presence of a still functional DSB repair machinery which sets a barrier on invasive tumor growth, thereby keeping E2F1 at the ‘bright side’ of DNA repair." (PMID 31287003, 2019). "Therefore, even though maybe the RB pathway is not always aberrant at the genomic level (deletions of RB or p16/CDKN2A, amplifications of cyclins or CDKs), there is always E2F1 free owing to uncontrolled replication of tumor cells." (PMID 31138805, 2019). "Therefore, inhibiting E2F1 activity could potentially impact tumor development at different levels simultaneously by blocking cell cycle progression and by impairing metabolic flexibility in cancer cells." (PMID 29176962, 2017). "Since the MIR136-5p expression itself was downregulated in the tumor tissue, we could not rule out whether E2F1 higher expression was only due to the target site mutation." (PMID 28704519, 2017). "Finally, although phosphorylation of S332, S337 and S375 is important for E2F1 association with the retinoblastoma protein, transcriptional activity and protection from degradation in tumour cell lines, these residues are also dispensable for E2F1 degradation in differentiating keratinocytes." (PMID 27903963, 2017). "Therefore, E2F1 molecular targeting may be a beneficial therapeutic strategy for certain aggressive tumor phenotypes." (PMID 27613060, 2016). "Therefore, E2F1 may act as an oncogene or a tumor suppressor depending on tumor cell context i.e., E2F1 is mediating either cell proliferation and growth or tumor suppresion and apoptosis." (PMID 26831819, 2016). "Accordingly, the levels of E2F1 were significantly increased in TACO expressing HCC tissue, suggesting that HBV CP mutations may induce hepatocarcinogenesis and tumour progression via similar mechanisms." (PMID 27779207, 2016). "E2F1, which is highly expressed in tumor cells, may also contribute to Ect2 up-regulation." (PMID 27074761, 2016). "Interestingly, E2F1 has multiple functions that could be considered to be either suppressing or promoting tumor development." (PMID 27835866, 2016). "However, one might predict that there are specific downstream targets of E2F1 or E2F2 that mediate discreet steps in the development of tumor metastasis." (PMID 26682278, 2015). "Because E2F1 and FOXOs are not normally simultaneously functional in the nucleus, they require certain oncogenic stresses, such as loss of RB function, to trigger an apoptotic response and suppress tumor emergence." (PMID 25907958, 2015).
tumor (continued). "Therefore, it is likely that, E2F1 might play an important role in mediating metformin-induced rapid tumor progression probably via regulating aerobic glycolysis." (PMID 26484566, 2015). "Although the major sources of inflammation cytokines in tumor microenviroment are coming from the infiltrated immune cells, the results implicated that the reduction of these cytokines in DU145/sh-E2F1 may also contribute to the inhibition of the tumor cell growth." (PMID 24742333, 2014). "This suggested that UV-induced E2F1 mediated apoptosis in skin may have tumour suppressive effects." (PMID 22272113, 2011). "The transcription factor E2F1 plays a pivotal role in the coordinated expression of genes necessary for cell cycle progression and division, and is known to be an oncoprotein critical for the transcriptional activation of genes that control the rate of tumor cell proliferation." (PMID 21655246, 2011). "Thus, HMGA1 could promote tumor progression by inducing a molecular program for cell cycle progression and proliferation with up-regulation of E2F1 and cyclins." (PMID 22053823, 2011). "Conversely, studies on the well characterized E2F-1 have indicated that it may have characteristics of both an oncogene, by promoting the proliferation of cells beyond their normal constraints, and as a tumor suppressor." (PMID 20805990, 2010). "Thus, induction of E2F1 by T-oligos also contributes to tumor cell apoptosis." (PMID 20652008, 2010). "Also, one mechanism by which DDB2 plays a role in tumor cell proliferation could be related to its interaction with E2F1." (PMID 18431487, 2008). "As these tumours showed also more frequently decreased expression of E2F1 than other histological types and as a correlation between E2F1 and p14ARF was noted, this suggests that downregulation of p14ARF could be linked to the downregulation of E2F1 in this tumour type." (PMID 17117177, 2006). "Also, a role for the E2F1 gene as a tumour suppressor has recently been established through the generation of mice lacking a functional E2F1 allele." (PMID 12107831, 2002). "In turn, E2F1 activates the glucose-6-phosphate dehydrogenease (G6PD) transcription, driving NADPH production and metabolic reprogramming to support tumor growth and metastasis." (PMID 41484982, 2026). "The E2F family of transcription factors, particularly E2F1 and E2F7 which are often upregulated in tumors, are master regulators of cell cycle progression and are known to enhance tumor cell proliferation, angiogenesis, and invasiveness." (PMID 41584032, 2026). "This process is driven by transcription factors like E2F1 and FOXF1 which promote rapid tumor growth by activating cell cycle and apoptotic pathways that contribute to neovascularization." (PMID 41450739, 2025). "Treatment with abemaciclib of rats bearing esophageal adenocarcinoma xenografts, established from three different cell lines, resulted in tumor volume reduction and down-regulation of cyclin D, CDK4, CDK6 and E2F1, compared with rats treated with placebo." (PMID 40699853, 2025). "We observed that E2F1 protein expression was significantly increased in LUAD tissues compared to the adjacent tissues, and was positively correlated with tumor stage (P = 0.032), invasion (P = 0.049) and distant metastasis (P = 0.032)." (PMID 40886002, 2025).